GLIS1 (GLIS family zinc finger 1)
Diseases named in the same sentence as GLIS1 in open-access papers (continued):
Sharing a sentence is not in itself a finding about the gene and the disease.
tumor (6 papers, 2014 to 2024). "The expression of GLIS1 exhibited a notable inverse association with tumor purity and was positively correlated with the infiltration of various immune cells in PCa, including B cells, DC, CD4+ T cells, CD8+ T cells, macrophages, and neutrophils." (PMID 38203661, 2023). "We noticed an increase in tumor-promoting or a decrease in anti-tumorigenic transcripts, alongside an increased inflammatory potential associated with high Glis1 transcript levels in 2D." (PMID 36406265, 2022). "In this study, GLIS1 was positively associated with these chemokines/chemokine receptors, indicating that GLIS1 may enhance tumor immune infiltration levels via modulating the migration of immune cells in PCa." (PMID 38203661, 2023). "Using the TIMER database, we identified that GLIS1 exerted an influence on tumor-infiltrating immune cells in PCa." (PMID 38203661, 2023). "Concerning GO enrichment analysis, GLIS1 was found to be involved in several signaling pathways in tumor cells, which is similar to the GO analysis results of tDEGs in PRAD, revealing a high degree of correlation regulation." (PMID 38203661, 2023). "The expression of GLIS1 was found to be downregulated in a cohort of malignancies comparing tumor and normal tissues from independent datasets in the Genotype-Tissue Expression (GTEx) database and TCGA database." (PMID 38203661, 2023). "Considering the GSEA results found that GLIS1 was involved in tumor immune regulation, we next performed single-sample Gene Set Enrichment Analysis (ssGSEA) to detect the correlation between GLIS1 mRNA expression and immune cell infiltration levels in PCa." (PMID 38203661, 2023). "In summary, GLIS1 is a potential prognostic biomarker and a therapeutic target to modulate anti-tumor immune response in PCa." (PMID 38203661, 2023). "Additionally, we performed Gene Ontology (GO) analysis, Gene Set Enrichment Analysis (GSEA), and other methods to investigate the potential roles of GLIS1 in tumor development and tumor immune microenvironment." (PMID 38203661, 2023). "In our study, GLIS1 negatively regulated the infiltration of Th2 cells, which suggested that the decreased GLIS1 expression in PCa may help mediate the tumor immune escape." (PMID 38203661, 2023). "To determine whether GLIS1 in CAFs regulates tumor angiogenesis, we examined its effect on tube formation ability of HUVECs cultured with CAF-CM." (PMID 35216340, 2022). "To investigate the effects of CAF-derived GLIS1 on intraperitoneal tumor metastasis in vivo, we established xenograft tumor models through inoculation of a mixture of SKOV3 cells and CAFs transfected with siGLIS1 or Control siRNA at a 1:4 ratio in the peritoneal cavity of nude mice." (PMID 35216340, 2022). "Additionally, GLIS1 participated in the biological process of immune cells entering tumor tissues and improved the tumor microenvironment (TME) of patients, and thus may affect the development of PCa and patients’ prognosis." (PMID 38203661, 2023). "As a result, GLIS1 is involved in the regulation of TME in PCa by engaging in both cellular and humoral immunity and promoting anti-tumor activities." (PMID 38203661, 2023). "Hence, high GLIS1 expression may contribute to the migration of immune cells to the tumor tissues." (PMID 38203661, 2023). "Therefore, how GLIS1 participates in the TME and influences tumor-infiltrating immune cells in PCa deserves exploration." (PMID 38203661, 2023). "Further, histone lactylation in some (Pan Kla and H3K18la), but not all (H3K9me3 and H3K27me3) cultured tumour cells increased substantially after Glis1 overexpression and decreased after Glis1 knockdown." (PMID 33566386, 2022).
infection (2 papers, 2018 to 2025). The state of being infected such as from the introduction of a foreign agent such as serum, vaccine, antigenic substance or organism. "For this purpose, we overexpressed GLIS1 protein in FACS-sorted satellite cells by infection with GLIS1-mCh adenovirus and differentiated them in adipogenic medium for 7 days." (PMID 29371665, 2018).
GLIS1 also shares sentences with these, for which no sentence is quoted: encephalitis (2 papers); amyotrophic lateral sclerosis (1); autism (1); autoimmune disease (1); chordoma (1); glioma (1); melanoma (1); ocular hypertension (1); Parkinson disease (1); prostate carcinoma (1); psoriasis (1); sarcoma (1).